MIR7850 (microRNA 7850)
Synonyms: hsa-mir-7850
Gene: MicroRNA gene on chromosome 19 (2,630,715 to 2,630,793, forward strand). Ensembl gene ENSG00000277904.
Homologues: Orthologues: chimpanzee MIR7850 (100% identical), macaque MIR7850 (100% identical).